BDNF (brain derived neurotrophic factor)
Diseases named in the same sentence as BDNF in open-access papers (continued):
Sharing a sentence is not in itself a finding about the gene and the disease.
asthma (continued). "For example, antibody blockage of NGF affected early inflammatory responses in murine asthma while neutralisation of BDNF reduced only chronic airway obstruction and BHR but not inflammation." (PMID 16441896, 2006). "When patients were subdivided into those with or without AERD according to the presence or absence of the triad of clinical features (asthma, recurrent nasal polyps, and sensitivity to aspirin or other NSAIDs), nominally higher BDNF levels were observed in patients with AERD." (PMID 33114368, 2020). "Furthermore, asthma patients with sensitivity to aspirin (1.22 pg/mL, 0.93–1.77) had significantly higher BDNF levels in plasma (p = 0.009) than asthma patients lacking aspirin sensitivity (0.84 pg/mL, 0.57–1.18)." (PMID 33114368, 2020). "Thus, the lack of detrimental effects of LABAs on COPD control suggests that LABAs do not have the same effect on systemic BDNF concentrations in patients with COPD as in patients with asthma." (PMID 23245944, 2012). "Therefore, our findings imply that BDNF could serve as a potential biomarker of asthma, but not asthma severity." (PMID 33114368, 2020). "Likewise, NTs are detected in other bronchial smooth muscle cells during asthma or sarcoidosis and their relationship with inflammatory cytokines, IL-1β and interferon (IFN)-γ has been established by the induction of NGF, and BDNF mRNA expression and secretion in cell-culture supernatants." (PMID 25418464, 2014). "Secondly, in contrast to patients with asthma, neither inhaled nor oral corticosteroids had an impact on BDNF serum levels in patients with COPD, suggesting that patients with COPD and asthma might differ in their BDNF response to treatment." (PMID 23245944, 2012).
attention deficit-hyperactivity disorder (27 papers, 2013 to 2026). A disorder characterized by a marked pattern of inattention and/or hyperactivity-impulsivity that is inconsistent with developmental level and clearly interferes with functioning in at least two settings (e.g. at home and at school). "In a sample of individuals who had attempted suicide and in attention-deficit hyperactivity disorder patients, low blood BDNF concentrations were associated with high levels of impulsivity." (PMID 38721616, 2024). "The disturbed dopamine availability and brain-derived neurotrophic factor (BDNF) expression are due in part to be associated with attention deficit hyperactivity disorder (ADHD)." (PMID 28293263, 2017). "In addition, BDNF polymorphisms may affect the pathophysiology of many neuropsychiatric disorders, e.g., attention deficit hyperactivity disorder (ADHD), obsessive-compulsive disorder, and movement disorders, such as TS." (PMID 38706359, 2025). "Nevertheless, it has been shown that stimulating the expression of BDNF via physical exercise has a positive impact on the attention span of children with attention deficit hyperactivity disorder (ADHD)." (PMID 35628626, 2022). "We aimed to determine whether early parenting is associated with externalizing and internalizing symptoms in children with attention-deficit hyperactivity disorder (ADHD) and whether such an association is affected by the brain-derived neurotrophic factor (BDNF) val66met polymorphism." (PMID 25425456, 2014). "Attention-deficit/hyperactivity disorder (ADHD), brain-derived neurotrophic factor (BDNF), and enuresis are interconnected in several ways, primarily through their potential links to neurodevelopmental factors and brain function." (PMID 42041783, 2026). "Attention-deficit hyperactivity disorder (ADHD) is of key interest in this context, as multiple lines of evidence already link BDNF and ADHD." (PMID 35354099, 2022). "YY162 (200 mg/kg, per os, from PND 21 to PND 35) significantly attenuated the reduction of BDNF protein in the prefrontal cortex and ameliorated the ADHD- (attention deficit hyperactivity disorder-) like behavioral phenotype induced by Aroclor 1254." (PMID 29464125, 2017). "The aim of this research was to analyze the methylation profile of four well-known genes involved in neurodevelopment (BDNF, RELN, MTHFR and HTR1A) in the mothers of forty-five age-matched AS (Asperger Syndrome), ADHD (Attention Deficit Hyperactivity Disorder) and typically developing children." (PMID 36980856, 2023). "In a study on the effect of vitamin D3 in children with attention-deficit/hyperactivity disorder (ADHD), it was found that the level of 25D3 and dopamine increased in the supplemented group, while the serum BDNF and serotonin levels did not change significantly." (PMID 33924016, 2021).
gastric cancer (27 papers, 2014 to 2025). A primary or metastatic malignant neoplasm involving the stomach. "BDNF expression was reported to be associated with poor prognosis of gastric cancer." (PMID 36339684, 2022). "Finally, one biological factor was also identified as having a possible association with psychosocial functioning, whereby the Met allele of BDNF Val66Met may be predictive of an anxious coping style in patients with advanced gastric cancer." (PMID 37891568, 2023). "PTX3, elevated by BDNF/TrkB axis, is related to bone metastatic status of gastric cancer by enhancing gastric cancer-osteoblastic niche interactions." (PMID 41479916, 2025). "The migration-promoting effect of PTX3 in bone-metastatic gastric cancer cells aligns with another study that demonstrated PTX3 upregulation via the BDNF/TrkB axis, enhancing gastric cancer-osteoblastic niche interactions and contributing to bone metastasis." (PMID 41479916, 2025). "For example, miR-10 regulates the oncogene USF2 in myeloid leukaemia, BDNF in cervical cancer, and Tiam1 in gastric cancer." (PMID 35573695, 2022). "For example, Pereira found that the circHIPK3/miR-107/BDNF/LIN28 axis was related to chemoresistance in gastric cancer." (PMID 36606192, 2022). "Previous reports have demonstrated significant correlations of elevated BDNF/TrkB axis expression with disease progression and poor prognosis in patients with gastric cancer." (PMID 27458153, 2016). "The following steps occur once the cancer cells have invaded BM: first, BDNF derived from bone metastatic gastric cancer can stimulate TrkB on OBs to directly promote RANKL production." (PMID 27458153, 2016). "To verify the potential involvement of PTX3 in the BDNF-induced promotion of gastric cancer cell binding to OBs, we silenced PTX3 expression in HTB135 cells using PTX3-specific siRNA." (PMID 27458153, 2016). "Here we identified elevated expression of the BDNF/TrkB axis in human advanced gastric cancers with bone metastatic properties." (PMID 27458153, 2016). "The increased co-expression of the BDNF/TrkB axis was significantly correlated with bone metastatic properties in advanced gastric cancers." (PMID 27458153, 2016). "Similar to this RANKL–RANK axis, it is tempting to postulate that BDNF expressed by OBs promotes the migratory capacity of disseminated gastric cancer cells expressing elevated levels of TrkB, a specific receptor of BDNF." (PMID 27458153, 2016). "PTX3 protein, which is induced by the BDNF/TrkB axis, facilitates the interaction of gastric cancer cells with OBs, thereby suggesting a potential role of PTX3 in establishing bone metastatic footholds of gastric cancer cells in BM." (PMID 27458153, 2016). "The present study is the first to support a strong possible relationship between elevated BDNF/TrkB expression and bone metastatic potential in advanced-stage gastric cancers." (PMID 27458153, 2016). "Second, TrkB activation by BDNF, produced by metastatic advanced gastric cancer cells, can induce PTX3 expression in the bone microenvironment, thereby contributing to an inflammatory osteoclastogenic condition by stimulating RANKL production from OBs." (PMID 27458153, 2016). "Taken together, these results suggest that elevated TrkB and BDNF expression in advanced gastric cancer correlates with bone metastatic properties." (PMID 27458153, 2016). "BDNF acting via TrkB receptors increased the levels of long pentraxin 3 (PTX3) that was related to bone metastatic status of gastric cancer by enhancing gastric cancer–osteoblastic niche interactions." (PMID 27458153, 2016). "In this study, we investigated the clinical and biological significance of the BDNF/TrkB axis in the progression of human gastric cancer." (PMID 27458153, 2016). "Recently, we showed that the blockade of BDNF/TrkB signaling by K252a suppressed the PC formation arising from gastric cancer cells with co-expression of BDNF and TrkB." (PMID 24801982, 2014).
gastric cancer (continued). "More recently, we have demonstrated the involvement of the BDNF/TrkB pathway in tumor progression in gastric cancer." (PMID 24801982, 2014). "Specifically, two circRNAs, namely, cTFRC and circTCF25, were reported to sequester miR-107 in bladder cancer cells, thus favoring cell cycle progression, while in gastric cancer, circHIPK3 was shown to sponge miR-107, enabling the release of brain-derived neurotrophic factor (BDNF) expression." (PMID 32626702, 2020). "In addition, elevated expression of the BDNF/TrkB axis has been found to significantly correlate with disease progression and poor prognosis in gastric cancer in humans." (PMID 27458153, 2016). "Similarly, HTB135 bone metastatic cells expressed the highest level of BDNF mRNA among all gastric cancer cell lines (P <0.05)." (PMID 27458153, 2016). "The findings that TrkB activation is an obligatory event in PTX3 expression and, in turn, that PTX3 stimulates TrkB expression clearly support the idea that PTX3 is a possible mediator in the bone metastatic gastric cancer–OB interaction with respect to the BDNF/TrkB axis." (PMID 27458153, 2016). "Taken together, these results indicate that in addition to its positive effect on the interaction between bone metastatic gastric cancer cells and OBs, BDNF may play a functional role in enhancing osteoclastogenesis by upregulating PTX3, which in turn promotes RANKL production from OBs." (PMID 27458153, 2016). "In light of our finding that stage III gastric tumors express higher levels of TrkB mRNA, we next investigated through an immunohistochemistry (IHC) analysis whether the elevated protein levels of TrkB and BDNF would correlate with disease severity in patients with gastric cancer." (PMID 27458153, 2016). "Therefore, we reasoned that BDNF-derived PTX3 induction in bone metastatic gastric cancer cells may upregulate RANKL expression in OBs, thereby stimulating OC formation." (PMID 27458153, 2016). "This transformation, coupled with NF-κB activation, upregulates brain-derived neurotrophic factor (BDNF) expression, which affects gastric cancer cell sensitivity to anlotinib through the NTRK2/NFE2L2 pathway." (PMID 40038745, 2025). "Given the upregulation of BDNF/TrkB and PTX3 expression observed in bone metastatic gastric cancers, we assumed that BDNF, a specific ligand of TrkB, induces PTX3 expression via TrkB signaling in bone metastatic gastric cancer cells." (PMID 27458153, 2016). "BDNF stimulates long pentraxin 3 (PTX3) expression through TrkB, thereby promoting interactions between bone metastatic gastric cancer cells and OBs and subsequent osteoclastogenesis." (PMID 27458153, 2016). "Responders with gastric cancer (GC) had larger increases in brain-derived neurotrophic factor levels than nonresponders (44.77% [95% CI, 10.76% to 78.79%] vs −26.2% [95% CI, −58.53% to 6.12%]; P = .003)." (PMID 31339548, 2019). "In conclusion, we have demonstrated a functional interaction between BDNF/TrkB and PTX3 in advanced gastric cancer and have provided evidence that these proteins may enhance the interaction between bone metastatic gastric cancer cells and OBs, thereby leading to osteolysis." (PMID 27458153, 2016). "In HTB135 cells, PTX3 silencing completely obviated the BDNF-induced increase in HTB135 cell–OB interactions (P <0.05), suggesting that BDNF-induced PTX3 is the predominant factor responsible for the interaction of bone metastatic gastric cancer cells with OBs." (PMID 27458153, 2016). "Furthermore, an increase of BDNF after 2–3 weeks of therapy, but not the baseline level, correlated with response to therapy and better PFS in gastric cancer patients treated with immunotherapy." (PMID 39143551, 2024). "Conversely, PTX3 at a concentration of 100 ng/ml markedly stimulated the transcriptional expression of TrkB mRNA but not BDNF mRNA in HTB135 cells, implying the presence of reciprocal regulation between PTX3 and TrkB expression in bone metastasis of gastric cancer." (PMID 27458153, 2016).
Brain atrophy (26 papers, 2013 to 2025). Partial or complete wasting (loss) of brain tissue that was once present. "The overexpression of BDNF in the forebrain of YAC128 HD mice increased BDNF levels in the striatum, rescuing the abnormal spine phenotype of medium spiny neurons and preventing the loss of striatal neurons and brain atrophy." (PMID 41471389, 2025). "Overall, the study results indicate lower rates of brain atrophy and less pronounced signs of damage associated with BDNF." (PMID 39148705, 2024). "Despite not having a direct effect on protein structure, these intronic BDNF SNPs still are associated with brain atrophy and cognitive dysfunction." (PMID 36468063, 2022). "The same protective role of BDNF rs6265 polymorphism against brain atrophy was highlighted in other subsequent studies." (PMID 33815257, 2021). "Literature supports that BDNF levels decline during normal brain aging, which are often accompanied by mild brain atrophy, reduced neuronal function, and synaptic loss." (PMID 34421682, 2021). "Another feasible explanation is that the reduction of the serum BDNF level is caused by the loss of BDNF-secreting neurons as a consequence of acute brain injury and subsequent brain atrophy." (PMID 32565776, 2020). "Overall, the data pointed out that the BDNF Met-carriers might benefit from a protective effect of the polymorphism against brain atrophy in MS." (PMID 35265024, 2022). "Higher potential for secreting nutritional factors, better cell proliferation ability, better neural recovery, higher expression of BDNF, less brain atrophy." (PMID 41159140, 2025). "Animals receiving rCellSaics displayed better neurological recovery, higher intracerebral BDNF, and better cell engraftment; they also showed a tendency for less brain atrophy and higher benzodiazepine receptor preservation." (PMID 35966129, 2022). "Mimicking brain-derived neurotrophic factor (BDNF) action using small molecules (7,8-dihydroxyflavone and 4′-dimethylamino-7,8-dihydroxyflavone) in N171-82Q for example reduced motor deficits and brain atrophy, at least partially by mitigating impaired neurogenesis." (PMID 38731912, 2024). "As BDNF and NTRK2 play important role in neuronal maintenance and plasticity, identification of this upstream regulator will provide an important insight on molecular mechanism underlying brain atrophy and cell loss observed in the sgACC of MDD." (PMID 35280164, 2022). "Our results suggest that B401 treatment may effectively alleviate brain atrophy and enhance brain BDNF expression in 8-month 3× Tg-AD mice." (PMID 27761145, 2016). "Notably, the correlations between MRI parameters and BDNF secreting immune cells were lost in AD in whom, instead, brain atrophy was positively correlated with IL-21-producing CD4+ T cells." (PMID 24324435, 2013). "Similarly, we observed brain atrophy and a reduction in BDNF levels in UCCAO mice, suggesting that BDNF may be closely linked to brain atrophy." (PMID 37513692, 2023). "A recent study showed that brain atrophy in AN is less readily reversible in older, and therefore more chronic patients, and we conversely speculate that alterations in peripheral BDNF concentrations may be more easily detectable in patients with a more chronic clinical course." (PMID 33572701, 2021). "However, we also found that the reduction of serum BDNF does not remain constant over time; the BDNF level progressively tends to normalize, not supporting the argument that its reduction is due mainly to the loss of neurons with progressive brain atrophy." (PMID 32565776, 2020). "In addition, oral herbal formula B401 treatment effectively alleviates brain atrophy and enhances brain BDNF expression, improves subcutaneous blood flow and enhances brain VEGF expression, and reduces blood ROS and enhances brain SOD2 expression but reduces brain 3-NT expression in 3× Tg-AD mice." (PMID 27761145, 2016).